CRP (C-reactive protein)
Diseases named in the same sentence as CRP in open-access papers (continued):
Sharing a sentence is not in itself a finding about the gene and the disease.
infection (continued). "IL-6 with an optimal cutoff value of 84.00 pg/mL (AUC 0.84), PCT with an optimal cutoff value of 1.39 ng/mL (AUC 0.80), CRP with an optimal cutoff value of 150.00 mg/L (AUC 0.76) on POD 3 had superior diagnostic accuracy in predicting postoperative infections." (PMID 38504206, 2024). "Elevated concentrations of C-reactive protein are considered a marker of underlying infection or inflammation." (PMID 39339938, 2024). "There are multiple other pathological situations, aside from infections, associated with an increase in CRP." (PMID 38302903, 2024). "We conducted a comprehensive assessment of the diagnostic potential of CRS, fever, PCT, IL-6, and CRP for the early detection of severe infection in febrile patients following CTI." (PMID 38956649, 2024). "It needs to be underlined that the patients with CRP values > 15 mg/L or any symptoms indicating infection were excluded from our study." (PMID 38255209, 2024). "In the absence of other histopathological abnormalities, combined with the positive immunohistochemical results, it is reasonable to believe that the elevated CRP in this patient was caused by infection with SARS-CoV-2." (PMID 37667198, 2023). "One potential area of research would be to combine molecular diagnostic tools with CRP testing to understand how CRP levels respond to various sources of infection." (PMID 36673130, 2023). "Further multivariate logistic regression analysis showed that high serum levels of CRP and decreased platelets at pre-infected laboratory examination were identified independent risk factors for infection in N-DLBCL treatment in our study." (PMID 37864133, 2023). "Considering the role of native CRP in host defense, therapies aimed at reducing serum pCRP level would likely impair defense mechanisms and predispose to infection." (PMID 37564640, 2023). "This is expected since CRP is elevated following infection or inflammation, with higher levels indicating severe infection; the latter linked to hospitalization." (PMID 37228441, 2023). "Given the low specificity of CRP to diagnose postoperative infection after CRS/HIPEC, we assessed the diagnostic value of PCT in this setting." (PMID 36631814, 2023). "Observational studies have demonstrated that CRP behaviour during antibiotic therapy is highly associated with mortality among hospitalized patients with severe infections." (PMID 37138222, 2023). "The almost double CRP and much higher IL-6 values indicate that the pro-inflammatory picture is much more pronounced during the infection with this variant." (PMID 37834972, 2023). "The only clinical factors associated with a higher risk of severe infection were oxygen saturation < 95% (p = 0.015) and elevated C-reactive protein (p = 0.03)." (PMID 37111403, 2023). "In their study which focussed on the correlation of contamination of the graft with clinical infection and its association with C-reactive protein (CRP) and erythrocyte sedimentation rate (ESR), they collected two tissue samples from each graft for culture." (PMID 37561186, 2023). "CRP had better diagnostic accuracy than X-rays in predicting late chronic and early postoperative infections." (PMID 37189111, 2023). "They concluded that severe COVID-19 disease was associated with significantly increased neutrophils, infection biomarkers (such as CRP), and cytokine levels and decreased lymphocyte counts." (PMID 36838284, 2023). "At the same time, a large of pro-inflammatory cytokines (interleukin-6, C-reactive protein, tumor necrosis factor-α, etc.)are synthesized and secreted upon pathogenic infection." (PMID 38223568, 2023). "Regarding viral pneumonia, some data have shown an association of higher levels of CRP with the severity of the infection." (PMID 36671362, 2023). "Other data have revealed that in chronic lymphatic obstruction, even during pathogenic infections, CRP is elevated [1225]." (PMID 37873776, 2023).
infection (continued). "In our study, the AUC (0.744 and 0.754; p = 0.7926) and the diagnostic performance of the different levels of PCT and CRP are comparable in detecting acquired infections during ICU stay." (PMID 37887237, 2023). "Delta CRP and hospitalization days were associated with higher all-cause infection rates in univariable analysis, but only Delta CRP independently predicted all-cause infection in multivariable analysis." (PMID 37189057, 2023). "Although data on the diagnostic accuracy of CRP in differentiating infection from non-infection are inconclusive, simultaneous measurement of WBC and CRP provides moderate discrimination." (PMID 37510151, 2023). "Infections of the recipient with this pathogen were associated with significantly higher values of CRP." (PMID 36839578, 2023). "At this point we were able to conclude that the initial values of distinct inflammatory biomarkers are good or excellent predictors for disease severity (e.g., CRP), Delta variant infection (e.g., suPAR) and mortality (e.g., LDH, sTREM-1, HGF, suPAR)." (PMID 37388734, 2023). "Normal CRP values are less than 5 mg/dL, and 10 mg/L values are considered to indicate high risk of infection or severe inflammation." (PMID 36836567, 2023). "In humans, the C- reactive protein CRP is a protein with expression that increase more than 1,000-fold in acute-phase responses associated with a severe inflammatory state, trauma and infection." (PMID 37564652, 2023). "In 2017, we started using baricitinib in a GCA patient with inadequate response to corticosteroids and where the abolishment of CRP reaction by TCZ in case of infection would have caused problems." (PMID 37304255, 2023). "Nevertheless, an elevated vaginal fluid CRP concentration (>10 mg/L) is possibly a risk factor for intra-amniotic inflammation or/and infection and impending preterm delivery in preterm PPROM." (PMID 37873776, 2023). "Laboratory measurement of CRP is a useful diagnostic tool to assist with diagnosis of infection, including within the spine, and the level will often normalize with treatment." (PMID 37483708, 2023). "In general, ESR and CRP are positively correlated with increased inflammatory material in the body and their increase indirectly reflects an increased risk of postoperative infection." (PMID 37563683, 2023). "The inflammatory conditions and host responses to infection cause the release of interleukin-6 and other cytokines that trigger the synthesis of CRP and fibrinogen by the liver." (PMID 37461754, 2023). "The risk of infection is increased when abnormal CRP responses are seen 5 or 7 days following surgery." (PMID 37915948, 2023). "Patient A’s CRP arose after the earlier infection and reached its peak at 9.63 mg/L, seemingly associated with the dosage of the immunosuppression therapy." (PMID 36774503, 2023). "The Delta CRP at 24 h was the most important predictor of peristomal wound infection and all-cause infection within 14 days after PEG implantation." (PMID 37189057, 2023). "In our study, elevated CRP levels and SaO2 < 95% were associated with a higher risk of serious infection." (PMID 37111403, 2023). "Higher CRP values indicated a more severe infection and predict a higher risk of progression from a focal to a systemic infection." (PMID 37768395, 2023). "The elevated CRP levels during the postoperative period are known to be closely associated with postoperative complications including infections." (PMID 37731439, 2023). "The recognized risk factors for infection were age, total number of hospitalized wards, absolute neutrophil count, and C-reactive protein (CRP)." (PMID 36978383, 2023). "CRP, one of the acute phase proteins produced by liver cells, is associated with the severity of infection, acute inflammation, and chronic inflammation." (PMID 37653091, 2023).
infection (continued). "In another meta-analysis targeting pediatric patients aged 1 month to less than 18 years of age with fever, it was reported that CRP and procalcitonin provided the most diagnostic value in finding serious infection among inflammatory markers." (PMID 36670711, 2023). "Multivariate logistic models showed that PCT ≥ 0.16 ng/mL and CRP ≥ 1.35 mg/dL were associated (p < 0.001) with infections acquired during ICU stay." (PMID 37887237, 2023). "Our study observed that elevated serum levels of CRP at pre-infected laboratory examination served as an independent risk factor for infection complications in N-DLBCL treatment." (PMID 37864133, 2023). "The heavier the HIE, the higher the risk of hs-CRP elevation after TH; The hs-CRP elevation has little to do with infection, and it doesn't recommend using antibiotics actively." (PMID 37168805, 2023). "Increased levels of biochemical parameters, such as procalcitonin, fibrinogen, CRP, or hemogram parameters, were linked with infection severity, ICU admission as well as mortality in previous studies." (PMID 36766961, 2023). "Specifically, a high C-reactive protein at admission has been associated with a more severe course of infection." (PMID 36173714, 2023). "Despite its low specificity, CRP is a helpful marker in a lot of acute conditions characterized by inflammation/infection, and its elevation was shown to be associated with a bad outcome in cardiovascular diseases." (PMID 37373750, 2023). "The best cut-off points of Delta CRP for the diagnosis of all-cause infection was 3 mg/dl, with a sensitivity of 53.85%, specificity of 81.08%, PPV of 50%, NPV of 83.33%, and accuracy of 74%." (PMID 37189057, 2023). "Our study showed that the KSRI-SF undifferentiated type and high CRP levels at initial infection were associated with PI-IBS." (PMID 37945663, 2023). "is an emergent pathogen causing a low-grade infection (CRP and other clinical and laboratory parameters are often negative)." (PMID 37349686, 2023). "Any 10% increase in LDH, CRP, and ferritin was similarly associated with an 11.28, 2.48, and 3.0% increase in GM of IgG concentration at 6 months post-infection." (PMID 37293303, 2023). "A low PWR was correlated with older age, a higher hemoglobin level, higher ALT level, lower albumin level, increased CRP level and infections with unidentified causative pathogens." (PMID 36292245, 2022). "In general, CRP is known to have a higher diagnostic accuracy for infection than that of WBC or ESR." (PMID 36138789, 2022). "We show that elevated CRP is highly prevalent in many morbidities and is associated with a greater relative risk of infection death than cardiovascular or other causes of death, irrespective of the CRP threshold chosen." (PMID 35535512, 2022). "During the decline, if the CRP level increased again, it indicated that the patient was at a risk of infection." (PMID 35813227, 2022). "Biological studies identified various mechanisms of action such as C-reactive protein (CRP), which is a biomarker associated with infection and stress." (PMID 35682074, 2022). "CRP levels measured on postoperative Day-3 had very good diagnostic accuracy for diagnosing infection at 14th and 28th day post-surgery respectively (AUC=0.819 and 0.818)." (PMID 35991254, 2022). "Cardiothoracic ratio has been found to be positively associated with C-reactive protein and inversely associated with albumin, and can predict 2-year all-cause mortality and infection-caused mortality in HD populations." (PMID 35055386, 2022). "In contrast, CRP levels at day three had good diagnostic accuracy for diagnosing infection at 14th and 28th day post-surgery (AUC=0.819 and 0.818 respectively) (Table-II)." (PMID 35991254, 2022). "A small but statistically significant association of IL-6 and C-reactive protein is linked to developing infection-related and -unrelated malignancies." (PMID 35453518, 2022).
infection (continued). "The infection of C. perfringens caused a heightened tendency on the concentrations of LPS, IL-6, CRP and PCT (0.05 < P < 0.10), and an increase on the activity of MPO (P < 0.05) in serum of broilers." (PMID 35436978, 2022). "D-dimer was introduced in 2018 as an alternative biomarker for C-reactive protein (CRP) in the diagnostic of prosthetic joint infection (PJI) criteria of the Musculoskeletal Infection Society." (PMID 35086474, 2022). "Systemic inflammation assessed using C-reactive protein is common in many chronic diseases and is associated with increased long-term risk of fatal infection." (PMID 35535512, 2022). "Presumably, most infections in our study were lower UTIs causing only a limited inflammatory response and therefore low CRP levels." (PMID 35255822, 2022). "C-reactive protein (CRP) is often used clinically as a rapid marker of inflammation caused by infection." (PMID 36189292, 2022). "The authors suggested that the prognostic value of CRP should be explained by the presence of infection or altered inflammatory response, both conditions associated with elevated CRP levels." (PMID 35308545, 2022). "Given the association between neurological symptoms and infection, we also assessed the levels of the inflammatory reactant CRP in plasma isolated from the HC and MS groups." (PMID 35335126, 2022). "CRP levels at admission had poor diagnostic accuracy for diagnosing infection at 14th and 28th day post-surgery respectively (AUC=0.490 and 0.447)." (PMID 35991254, 2022). "The goal of the analysis reported here was to assess the association between infection as indicated by the acute phase proteins, CRP and AGP, and as reported by maternal recall and the nutritional status of infants." (PMID 36211493, 2022). "The increases in ESR and CRP were important risk factors for postoperative infection, and the time of CRP reaction was related to the time of treatment." (PMID 35813227, 2022). "Two cytokines directly related to signs of infection or injury and loss of muscle mass are, respectively, C-reactive protein (CRP) and growth differentiation factor-15 (GDF-15)." (PMID 36499366, 2022). "Because CRP or PCT alone has limitations as a diagnostic purposes of infection (particularly its severity), it would be helpful to examine the combined inflammatory biomarkers while considering diagnostic stewardship with avoidance of over-tests." (PMID 36555941, 2022). "Eleven parameters showed a significant association with an infection including C-reactive protein, albumin, creatinine, and alcoholic etiology, which were independent variables in a predictive model." (PMID 36057565, 2022). "Surrogate indicators of infection (ferritin, C-reactive protein (CRP)) associated with IL-6 are of growing importance for prognostic usefulness; however, expensive cytokine analysis is not regularly conducted in most laboratories." (PMID 36547111, 2022). "CRP levels measured on post-op Day-3 (cutoff value 230mg/dl) had good diagnostic accuracy for diagnosing infection at 14th and 28th day post-surgery respectively (AUC=0.819 and 0.818)." (PMID 35991254, 2022). "Separately, CRP, a diagnostic marker of RA in clinical practice, is significantly elevated in plasma levels in response to infection, inflammatory stimuli, or other tissue damage in the acute phase." (PMID 35603148, 2022). "Multivariate analysis also confirmed that CRP level was a risk factor for the occurrence of infection in children with AL." (PMID 35463661, 2022). "We found that VTE episodes after 12 months following a new diagnosis of AAV were associated with inflammation in that they appeared to occur in association with a disease relapse, severe infection or elevated CRP." (PMID 35948984, 2022). "Of note, tocilizumab increases the risk of infection, and it hampers the recognition of an infection by diminishing the fever response and the levels of C-reactive protein." (PMID 35060089, 2022).
infection (continued). "The results of the univariate ordinal logistic analysis showed that CRP at Days 4−7 and 8−14, IL‐6 at Days 4−7, and total antibody were significantly associated with the infection severity." (PMID 35759224, 2022). "Based on a random forest model analysis, PLT, age, MAP, CRP, and HR were the top five clinical features associated with infection." (PMID 35979059, 2022). "Previous studies have identified that increased CRP had a significant association with trauma, inflammation, and infection." (PMID 36434736, 2022). "The major findings of this prospective observational study of 201 children who were admitted to our PICU were that the nCD64 index at admission can be used to identify early childhood infection, and it provided greater diagnostic value than CRP or PCT." (PMID 36522701, 2022). "Multivariate logistic regression analysis showed that CRP, duration of EF, and Gustilo fracture type were independently associated with postoperative infection." (PMID 35813227, 2022). "Low-virulent microorganisms and patients with probable and possible infections are associated with lower CRP levels compared to patients with definitive infection and infections caused by high-virulent microorganisms." (PMID 33515325, 2022). "Results showed that CRP levels at admission had poor diagnostic accuracy for diagnosing infection at the14th and 28th days post-surgery (AUC=0.490 and 0.447 respectively) (Table -II)." (PMID 35991254, 2022). "They differ between themselves by their respective levels of certainty of the causal infection, of CRP and ferritin levels, of renal and hemodynamic level of support, and of pro-inflammatory and anti-inflammatory activities." (PMID 36301921, 2022). "Multivariate logistic regression analysis demonstrated that the presepsin level higher than 980 pg/mL represents a factor associated with the diagnosis of infections in patients with LC and overt HE, along with the CRP value of more than 2.81 mg/dL." (PMID 36140479, 2022). "Given the close association between CRP and postoperative morbidity, Lizuka and Lindqvist assessed the potential use of CRP as an early indicator of infection/aseptic inflammation." (PMID 35743954, 2022). "In the context of broadening clinical use of anti-inflammatory therapies, our data caution that people identified as candidates based on elevated CRP are already predisposed to fatal infection before initiating treatment." (PMID 35535512, 2022). "Because elevated CRP was still associated with greater risk of infection death than other causes of death in these subgroups, it is possible that the combination of elevated CRP and these diseases identifies people particularly predisposed to infection death." (PMID 35535512, 2022). "To understand the virulence potential of sublethally injured C. jejuni causing clinical infection, we investigated the expression of the host stress response and defense genes CRP, MBL1, and NF-κB1." (PMID 35862957, 2022). "Because elevated CRP was more strongly associated with infection death than cardiovascular or other causes of death in all but 1 of the morbidities we studied, a common mechanism (or mechanisms) seems the most plausible explanation." (PMID 35535512, 2022). "Changes in CRP levels generally indicate systemic spread and are associated with other clinically apparent signs of infection, whilst neutrophil enzymes elevate locally well before systemic signs elevate." (PMID 36292097, 2022). "High levels of CRP have been associated with mortality from this infection, and CRP has been identified as a molecule capable of causing damage during SARS‐CoV‐2 infection." (PMID 36166345, 2022). "The diagnostic accuracy of CRP for diagnosing postoperative infections after hip surgery is questionable." (PMID 35991254, 2022). "In this study, our objective was to determine the diagnostic accuracy of C-reactive protein and to assess its validity as a reliable marker of postoperative infection after hip fracture surgery." (PMID 35991254, 2022).